GBA1 (glucosylceramidase beta 1)
Diseases named in the same sentence as GBA1 in open-access papers (continued):
Sharing a sentence is not in itself a finding about the gene and the disease.
Parkinson disease (continued). "The discovery of mutations in LRRK2 and GBA1 that are linked to Parkinson’s disease provided further evidence that autophagy and lysosome pathways are likely implicated in the pathogenic process." (PMID 36085537, 2023). "A specific focus has been placed on ambroxol’s glucocerebrosidase-stimulating activity, on grounds that the point mutation of the gba1 gene, which codes for this enzyme, is a risk factor for developing Parkinson’s disease." (PMID 37065090, 2023). "Parkinson’s disease (PD) patients who are carriers of glucosylceramidase β1 (GBA1) gene mutations typically have an earlier age at onset and a more aggressive disease course, with a higher burden of neuropsychological issues." (PMID 37122287, 2023). "The link between monoallelic GBA1 mutations and PD emerged between 1985 and 1988 when parkinsonism was described as a possible neurological manifestation in GD patients and their relatives carrying heterozygous GBA1 mutations." (PMID 37047309, 2023). "Multiple studies have implicated heterozygous GBA1 mutations as a major genetic risk factor for Parkinson's disease." (PMID 36776904, 2023). "After the initial reports of an increased incidence of Parkinson’s disease (PD) in patients affected by GD type I and in their family members, GBA1 mutations have been identified as the most frequent genetic risk factor for PD1,2." (PMID 37024507, 2023). "Most heterozygous mutations in the GBA1 gene elevate the risk of Parkinson’s disease and dementia with Lewy bodies." (PMID 37833892, 2023). "Heterozygous mutations in GBA1, which encodes the lysosomal hydrolase glucocerebrosidase (GCase), are a common risk factor for the neurodegenerative movement disorder Parkinson's disease (PD)." (PMID 37908374, 2023). "Now, it is clear that the presence of GBA1 mutation in homozygous or heterozygous form is associated with an approximately 20-fold increase in the risk for Parkinson disease (PD)." (PMID 35711931, 2022). "Variants in the GBA1 gene are strong genetic risk factors for developing sporadic Parkinson’s disease (PD)." (PMID 35941142, 2022). "We performed a systematic review with meta-analysis to explore the prevalence and the odds ratio of specific GBA1 variants in Parkinson’s disease in Latin America." (PMID 35941142, 2022). "Mutations in GBA1 are among the most common known genetic risk factors for the development of Parkinson’s disease in humans." (PMID 36077322, 2022). "There was an increase in the levels of phosphatidylcholine, with a simultaneous decrease in lyso-phosphatidylcholine, in the Gaucher, Parkinson’s and GBA1-mutation-carrier Parkinson’s patients vs. controls." (PMID 36142296, 2022). "An association between GBA1 variants and Parkinson’s Disease (PD) has been recognised and GD-related PD and nGD are probably distinct but related neuropathological processes, the further investigation of which will aid better understanding of each." (PMID 35717194, 2022). "For that, 278 participants were included: 100 sporadic Parkinson’s patients, 70 Gaucher patients, 15 GBA1-mutation-carrier Parkinson’s patients and 93 controls." (PMID 36142296, 2022). "Mutations in GBA1 are associated with an increased incidence of Parkinson’s disease (PD), both in GD patients and in heterozygous carriers, representing the main genetic risk factor for the development of PD." (PMID 35954187, 2022). "The mutations in GBA1 gene have been considered as the most common genetic risk factor for Parkinson’s disease (PD)." (PMID 36204141, 2022). "Mutations in the GBA1 gene encoding glucocerebrosidase (GCase) are linked to Gaucher (GD) and Parkinson’s Disease (PD)." (PMID 33727605, 2021). "Mutations in the GBA1 gene coding for glucocerebrosidase (GCase) are the main genetic risk factor for Parkinson’s disease (PD)." (PMID 34062940, 2021). "Considering the ongoing drug development targeting the GBA1 pathway, more and more people with Parkinson’s disease will be screened for GBA1 variants." (PMID 33420335, 2021).
Parkinson disease (continued). "Observations made by immunofluorescence staining of dopaminergic neurons of patients with Parkinson’s that carry mutations in the GBA1 gene reveal that their lysosomes display a larger size." (PMID 34957117, 2021). "Mutations in GBA1, which encode for the protein glucocerebrosidase (GCase), are the most common genetic risk factor for Parkinson's disease and dementia with Lewy bodies." (PMID 34613624, 2021). "Mutations in GBA1 have been identified as the most common genetic risk factor for developing earlier onset and more rapidly progressive Parkinson’s disease, even in those who have only one mutant GBA1 allele." (PMID 34571934, 2021). "PR001 is currently being evaluated in clinical trials with Parkinson’s disease patients carrying GBA1 mutations." (PMID 34151863, 2021). "Together, our work demonstrates a potential role of mitochondria-lysosome contacts as an upstream regulator of mitochondrial function and dynamics in midbrain dopaminergic neurons in GBA1-linked Parkinson’s disease." (PMID 33753743, 2021). "Gaucher disease is arguably the most characterized iPSC model of lysosomal disorders, probably owing to the fact that mutations in the glucocerebrosidase gene (GBA1) constitute an important genetic risk factor for Parkinson’s disease (PD)." (PMID 34241766, 2021). "GBA1 mutationsalso enhance the risk for Parkinson’s disease, whose hallmarkis the aggregation of α-synuclein (αSyn)." (PMID 34213307, 2021). "It is worth noting that a close link between Gaucher and Parkinson diseases has been established: GBA1 gene mutations are the highest risk factor for Parkinson disease." (PMID 32660097, 2020). "In recent years GBA1 mutations were repeatedly linked to Parkinson’s disease, suggesting that Parkinson’s disease patients present GBA1 mutations significantly more frequently than healthy control groups." (PMID 31929594, 2020). "The link between GBA1 mutations and α-synuclein accumulation, a hallmark of Parkinson disease, is not fully understood." (PMID 32833982, 2020). "Dutch Parkinson's disease patients display one of the largest frequencies of GBA1 variants reported so far, consisting in large part of the mild p.E326K variant and the more severe Dutch p.D140H + p.E326K founder allele." (PMID 32618053, 2020). "The most common genetic risk factor for Parkinson's disease known is a damaging variant in the GBA1 gene." (PMID 32618053, 2020). "Heterozygous carriers of many missense mutations in the GBA1 gene have dramatically increased risk of Parkinson’s disease." (PMID 32499675, 2020). "Mutations in glucocerebrosidase 1 (GBA1) represent the most common genetic risk factor for Parkinson disease." (PMID 32833982, 2020). "Patients carrying GBA1 mutations have an increased risk of developing Parkinson disease and Dementia with Lewy bodies." (PMID 31929594, 2020). "Insights into the inverse relationship between glucocerebrosidase and alpha-synuclein have led to new therapeutic approaches for the treatment of Gaucher disease and GBA1-associated Parkinson disease." (PMID 32509770, 2020). "Mutations in the glucocerebrosidase gene (GBA1), implicated in the rare, autosomal recessive lysosomal disorder Gaucher disease, are the most common known genetic risk factor for Parkinson disease." (PMID 32509770, 2020). "An increased risk of the development of Parkinson disease exists in patients with GD and carriers of mutations in GBA1." (PMID 33050940, 2020). "Parkinson’s disease patients bearing GBA1 mutation, tend to have earlier onset, a greater prevalence of cognitive decline as well as more severe cognitive impairment compared to those without the mutation." (PMID 30738426, 2019). "Mutations in GBA1, the gene encoding the lysosomal enzyme glucocerebrosidase, are among the most common known genetic risk factors for the development of Parkinson disease and related synucleinopathies." (PMID 31464647, 2019).
Parkinson disease (continued). "Currently brain penetrant forms of SRT are in clinical trials for patients with Parkinson disease who are heterozygous carriers of GBA1 mutations." (PMID 31464647, 2019). "Pilot studies conducted with brain bank samples, and in Parkinson disease clinics, suggested that patients with Parkinson disease sometimes carried GBA1 mutations." (PMID 31464647, 2019). "Today it is estimated that between 7 and 12% of patients with Parkinson disease carry a GBA1 mutation." (PMID 31464647, 2019). "Mutations in BIN1 are thought to induce early-onset Parkinson disease in patients with at least one mutated GBA1 allele." (PMID 31464647, 2019). "Despite the increased risk of developing parkinsonism among GBA1 mutation carriers, it is important to emphasize that only a minority of carriers with GBA1 mutations ever develop Parkinson disease." (PMID 31464647, 2019). "While no potential mechanism has been described for these mutations, it is possible that the combined effect of the mutation with assorted environmental or non-GBA1 genetic factors induce a higher risk for Parkinson disease." (PMID 31464647, 2019). "Previous studies using iPSC-derived dopaminergic neurons from Parkinson’s patients with GBA1 mutations identified disrupted Ca2+ homeostasis and increased vulnerability to stress responses that were rescued by isogenic correction." (PMID 31704946, 2019). "Ultimately, studies in large Parkinson disease cohorts and a multicenter international collaborative study established that in Parkinson disease world-wide, the odds ratio for a mutation in GBA1 was greater than five." (PMID 31464647, 2019). "The frequency varies depending on the population; for example, since the carrier frequency of GBA1 mutations is much higher among Ashkenazi Jews, over 15% of Ashkenazi Jewish patients with Parkinson disease carry at least one common GBA1 mutation." (PMID 31464647, 2019). "Mutations in LRRK2 and GBA1, which encodes glucocerebrosidase (GCase), are associated with Parkinson’s disease." (PMID 31804465, 2019). "One of the leading genetic risk factors for Parkinson's disease is being a carrier in the gene for β-Glucocerebrosidase (GCase; gene name GBA1)." (PMID 30738426, 2019). "GBA1 mutations are associated with more rapidly progressive clinical parkinsonism, earlier onset of cognitive impairment and advanced SYN pathology in the absence of AD co-pathology." (PMID 30473927, 2018). "Studies addressing the pathological mechanisms underlying GBA associated Parkinsonism will help in designing treatment strategies for Parkinsonism in patients with GBA1 mutation." (PMID 29503608, 2018). "GBA1 mutations reduce GCase activity, therefore promoting the aggregation of alpha-synuclein, a common neuropathological finding underlying Parkinson’s disease (PD) and dementia with Lewy bodies." (PMID 28835999, 2018). "Heterozygous mutations in glucocerebrosidase 1 (GBA1) are a major genetic risk factor for Parkinson’s disease and Dementia with Lewy bodies." (PMID 29703245, 2018). "Mutations in GBA1 leads to GBA1 enzyme deficiency, and GBA1-associated parkinsonism has an earlier age of onset and more progressive parkinsonism." (PMID 29703245, 2018). "Missense mutations in glucocerebrosidase (GBA1) that impair the activity of the encoded lysosomal lipid metabolism enzyme (GCase) are linked to an increased risk of Parkinson’s disease." (PMID 30337601, 2018). "The molecular mechanisms underlying the link between GBA1 mutations and Parkinson’s disease are incompletely understood." (PMID 28969384, 2017). "Mutations in GBA1 are important and common risk factors for Parkinson’s disease and related disorders." (PMID 28933363, 2017). "Patients with type-1 GD—but also carriers of GBA1 mutation—have been found to be predisposed to developing Parkinson’s disease, and the risk of neoplasia associated with the disease is still subject to discussion." (PMID 28218669, 2017).
Parkinson disease (continued). "Collectively, the data obtained from these studies clearly demonstrate the relationship between GCase deficiency and alpha-synuclein accumulation, and support the notion that Gba1 mutations can cause Parkinson's-like alpha-synuclein pathology in mice." (PMID 28969384, 2017). "Mutations in the GBA1 gene have been associated with Parkinson's disease (PD), the second most common neurodegenerative disorder after Alzheimer's disease, characterized by slow movements accompanied by decrement and degradation of repetitive movements." (PMID 29234271, 2017). "Mutations in glucocerebrosidase 1 (GBA1) represent the most prevalent risk factor for Parkinson’s disease." (PMID 28969384, 2017). "Recently, both heterozygous and homozygous mutations in the glucocerebrosidase 1 (GBA1) gene have been linked to Parkinson’s disease, with 10–30% of individuals with GBA1 mutations developing Parkinson’s disease by the age of 80." (PMID 28969384, 2017). "In general, GBA1-associated Parkinsonism often has an earlier age of onset (mean approximately 4–5 years earlier) and more prominent cognitive impairment, although some patients do well over prolonged periods of time." (PMID 28933363, 2017). "Studies in specific cohorts of patients with Parkinson’s disease and associated Lewy body disorders have indicated that these patients have an increased frequency of GBA1 mutations compared to control groups." (PMID 28933363, 2017). "Experimental and epidemiological evidence have strongly implicated an excess risk of Parkinson’s disease (PD) and Lewy body disease in GD type 1 patients, as well as heterozygote carriers of GBA1 mutations." (PMID 27598339, 2016). "Mutations in GBA1 are also a common genetic risk factor for Parkinson disease and related synucleinopathies." (PMID 27482815, 2016). "Recently, mutations in GBA1 were identified as the strongest genetic risk factor for Parkinson’s disease (PD) and dementia with Lewy bodies (DLB), which are neurodegenerative conditions characterized by intraneuronal protein aggregates containing α-synuclein." (PMID 27019408, 2016). "Mutations in β-glucocerebrosidase (encoded by GBA1) cause Gaucher disease (GD), a lysosomal storage disorder, and increase the risk of developing Parkinson disease (PD)." (PMID 26691915, 2016). "But both type I GD sufferers and carriers of GBA1 mutations are up to 20 times more likely to develop Parkinson disease (PD)." (PMID 26691915, 2016). "Lipidomic analyses and cholesterol measurements were performed on the putamen (n = 5‐7) and cerebellum (n = 7‐14) of controls, Parkinson's disease brains with heterozygote GBA1 mutations (PD+GBA), or sporadic PD." (PMID 26096906, 2015). "Loss of neuroprotection in this brain region is a common feature of LRRK2 and GBA1 mutations and may represent a convergent pathway contributing to Parkinson’s." (PMID 40737317, 2025). "Biallelic mutations in the GBA1 gene cause a lysosomal lipid storage disorder, Gaucher’s Disease (GD), while heterozygous mutations are known as the most common genetic risk factor for Parkinson’s Disease (PD)." (PMID 40649871, 2025). "Mice appeared healthy at the 6-month collection timepoint, and therefore future studies further extending the lifespan could be used to investigate potential alpha-synuclein pathology given the link of GBA1 mutations to Parkinson’s disease." (PMID 40430940, 2025). "Moreover, mutations in the GBA1 gene have been identified as a common risk factor for Parkinson’s Disease." (PMID 40430940, 2025). "The latest genome-wide association study (GWAS) in European derived populations identified common genetic variants associated with lysosomal dysfunction that contribute to Parkinson’s disease (PD) risk, with GBA1 (2025 PD GWAS, p.E365K (rs2230288, odds ratio [OR] = 1.66)) emerging as a key locus." (PMID 41331295, 2025).
Parkinson disease (continued). "In addition, such mutations are the highest genetic risk factor to develop Parkinson’s disease (PD) with at least 3-25% (depending on ethnicity) of PD patients carrying such a GBA1 variants and reduced GCase activity being a common symptom of PD15,16." (PMID 40159502, 2025). "Additionally, GBA-associated Parkinson’s disease (GBA1-PD) brains exhibit Lewy body pathology similar to that of sporadic PD but are reportedly more widespread." (PMID 40731814, 2025). "NPC1 is necessary for Rab8a‐mediated segregation of late endosomes from lysosomes, and lysosomal recycling is perturbed in GBA1‐mutated Parkinson disease fibroblasts, showing, in principle, the same could be true in nGD." (PMID 39822020, 2025). "The GBA1 gene has been established as a notable risk factor in Parkinson's disease (PD)." (PMID 40542290, 2025). "Mouse models of GBA1 deficiency have been indispensable for dissecting the mechanistic link between GD and Parkinson’s disease (PD), revealing how lysosomal dysfunction, glycosphingolipid accumulation, and α-synuclein pathology intersect to drive neurodegeneration." (PMID 41465340, 2025). "The link between GBA1 variants and Parkinson disease risk is well established." (PMID 39822020, 2025). "GBA1 has also been implicated in Parkinson’s disease and certain metabolic disorders when mutated." (PMID 40371365, 2025). "Mutations in GBA1, which encodes the lysosome enzyme β-glucocerebrosidase (also referred to as acid β-glucosidase or GCase), are the most common genetic risk factor for Parkinson’s disease (PD) and dementia with Lewy bodies (DLB)." (PMID 38251062, 2024). "This could explain the spread of Lewy bodies to limbic and neocortical areas of Parkinson’s disease patients with GBA1 mutations." (PMID 38978726, 2024). "In Parkinson’s disease (PD), GBA1- and LRRK2-mutations are associated with different clinical phenotypes which might be related to differential involvement of the cholinergic system." (PMID 38951174, 2024). "Patients carrying severe GBA1 mutations were associated with positive family history of parkinsonism and/or dementia, an earlier onset of disease, more profound cognitive decline, a higher prevalence of RBD, and decreased cerebrospinal fluid (CSF) levels of total α‐synuclein." (PMID 38641924, 2024). "Five-10% of patients with idiopathic PD, rising to 25% in Ashkenazi patients, are found to carry a GBA1 mutation/variant, underscoring not only the frequency of GBA1-associated PD but also the clinical similarities between this form of parkinsonism and the idiopathic disease." (PMID 39663354, 2024). "Interestingly, abnormalities in the GBA1 gene, encoding GBA1, have been linked to increased risk for Parkinson’s disease and Lewy-body dementia." (PMID 39395789, 2024). "In addition, GBA1 mutations serve as the most frequent genetic risk factor for synucleinopathies, such as Parkinson’s disease (PD) and dementia with Lewy bodies (DLB)." (PMID 38712038, 2024). "In this study, heterozygous expression of a common Parkinson-associated GBA1 variant, the L444P mutation, was found to exacerbate α-synuclein aggregation and spreading in a mouse model of Parkinson-like pathology targeting neurons of the medullary vagal system." (PMID 39663354, 2024). "Variants in GBA1 are also a common genetic risk factor for Parkinson disease (PD)." (PMID 37986861, 2023). "In vivo studies support the hypothesis that restoring normal levels of GBA1 activity can slow the progression of Parkinson’s disease in patients with mutations in the GBA1 gene." (PMID 36835039, 2023). "GBA1-associated Parkinsonism remains incompletely understood." (PMID 37629187, 2023). "Compared with the general population, patients with GD type 1 have a 20‐fold increased lifetime risk of developing parkinsonism, whereas individuals carrying heterozygous GBA1 mutations have a five times greater risk of developing PD than noncarrier individuals." (PMID 37219461, 2023).